MITF (melanocyte inducing transcription factor)
Description:
Transcription factor that acts as a master regulator of melanocyte survival and differentiation as well as melanosome biogenesis. Binds to M-boxes (5'-TCATGTG-3') and symmetrical DNA sequences (E-boxes) (5'-CACGTG-3') found in the promoter of pigmentation genes, such as tyrosinase (TYR). Involved in the cellular response to amino acid availability by acting downstream of MTOR: in the presence of nutrients, MITF phosphorylation by MTOR promotes its inactivation. Upon starvation or lysosomal stress, inhibition of MTOR induces MITF dephosphorylation, resulting in transcription factor activity. Plays an important role in melanocyte development by regulating the expression of tyrosinase (TYR) and tyrosinase-related protein 1 (TYRP1). Plays a critical role in the differentiation of various cell types, such as neural crest-derived melanocytes, mast cells, osteoclasts and optic cup-derived retinal pigment epithelium.
Synonyms: bHLHe32; MI; CMM8; COMMAD; MITF-A; WS2; WS2A
Tractability: Small molecule: it belongs to a druggable protein family. PROTAC: UniProt records ubiquitination sites on it; ubiquitination databases record sites on it; its protein half-life has been measured; a small molecule that binds it is known.
Target class: Transcription factor
Gene: Protein-coding gene on chromosome 3 (69,738,536 to 69,968,336, forward strand). Ensembl gene ENSG00000187098.
Subcellular location: Nucleus; Cytoplasm; Lysosome membrane
Pathways (Reactome):
Developmental Biology: Regulation of MITF-M dependent genes involved in invasion; Regulation of MITF-M dependent genes involved in metabolism; Regulation of MITF-M-dependent genes involved in DNA replication, damage repair and senescence; Regulation of MITF-M-dependent genes involved in apoptosis; Regulation of MITF-M-dependent genes involved in cell cycle and proliferation; Regulation of MITF-M-dependent genes involved in extracellular matrix, focal adhesion and epithelial-to-mesenchymal transition; Regulation of MITF-M-dependent genes involved in lysosome biogenesis and autophagy; Regulation of MITF-M-dependent genes involved in pigmentation; Transcriptional and post-translational regulation of MITF-M expression and activity
Metabolism of proteins: SUMOylation of transcription factors
Gene Ontology:
Molecular function: DNA-binding transcription activator activity, RNA polymerase II-specific; E-box binding; protein binding; RNA polymerase II cis-regulatory region sequence-specific DNA binding; DNA-binding transcription factor activity, RNA polymerase II-specific; DNA-binding transcription repressor activity, RNA polymerase II-specific; chromatin binding; DNA binding; DNA-binding transcription factor activity; protein dimerization activity
Biological process: negative regulation of cell migration; negative regulation of transcription by RNA polymerase II; positive regulation of DNA-templated transcription; positive regulation of DNA-templated transcription initiation; positive regulation of gene expression; positive regulation of transcription by RNA polymerase II; protein-containing complex assembly; regulation of DNA-templated transcription; regulation of RNA biosynthetic process; melanocyte differentiation; regulation of transcription by RNA polymerase II; developmental pigmentation
Cellular component: cytoplasm; lysosomal membrane; nucleus; protein-containing complex; chromatin; cytosol; nucleoplasm
Genetic constraint (gnomAD): Loss-of-function variants: 16 observed, 50.39 expected, observed/expected ratio (o/e) 0.32, 90% interval 0.21 to 0.48. The upper end of that interval is the gene's LOEUF score, 0.48, which puts it in group 2 of 6, group 1 being the genes least tolerant of losing a copy. Missense variants: 578 observed, 650.54 expected, observed/expected ratio (o/e) 0.89, 90% interval 0.83 to 0.95. Synonymous variants: 241 observed, 237.25 expected, observed/expected ratio (o/e) 1.02, 90% interval 0.91 to 1.13.
Gene-disease validity (ClinGen):
ClinGen rates the evidence that MITF causes each of these diseases.
Waardenburg syndrome type 2 (autosomal dominant): Definitive. Waardenburg syndrome type 2 (WS2) is an autosomal dominant subtype of Waardenburg syndrome (WS), characterized by varying degrees of deafness and pigmentation anomalies of eyes, hair and skin, but without dystopia canthorum.
Homologues: Orthologues: macaque MITF (99% identical), rabbit MITF (98% identical), guinea pig MITF (98% identical), pig MITF (97% identical), dog MITF (97% identical), mouse Mitf (94% identical), rat Mitf (94% identical), chimpanzee MITF (93% identical), tropical clawed frog mitf (77% identical), zebrafish mitfa (49% identical), Drosophila melanogaster Mitf (35% identical), Caenorhabditis elegans hlh-30 (26% identical). Paralogues in human: TFE3 (53% identical), TFEB (42% identical), TFEC (31% identical).
Diseases named in the same sentence as MITF in open-access papers:
MITF is named in the same sentence as 264 diseases in open-access papers, as found by Europe PMC text mining. Sharing a sentence is not in itself a finding about the gene and the disease. The quoted sentences say what the papers report.
melanoma (1,358 papers, 2008 to 2026). A malignant, usually aggressive tumor composed of atypical, neoplastic melanocytes. "In silico geometry optimization and docking were carried out for melanoma-associated targets (MITF and DNMT3B)." (PMID 41590097, 2026). "The authors identified 245 candidate lncRNAs associated with melanoma whose loci are jointly bound by MITF and SOX10, suggesting that DIRC3 exerts broad tumour-suppressive effects through IGFBP5-dependent mechanisms." (PMID 41463281, 2025). "The most frequently downregulated genes among the 4 cell lines were the melanoma markers MITF, S100, and KI67, which are useful for diagnostic or prognostic purposes." (PMID 40715046, 2025). "FAO genes (MYC, MITF, and CTNNB1) were enriched in the MYC+ cell cluster, and overexpression of MITF was associated with greater LN metastasis in mouse footpad melanoma." (PMID 39858514, 2025). "The first panel highlights melanoma-associated genes, including MITF, AXL, NGFR, TYRP1, and DCT, which are involved in the regulation of melanoma cell identity, dedifferentiation, and invasive potential." (PMID 40909289, 2025). "At the same time, the microphthalmia-associated transcription factor (MITF) is a key regulator of melanoma cell phenotype." (PMID 39976551, 2025). "sFRP2 also triggers a multi‐step signaling cascade in melanoma cells, leading to a reduction in β‐catenin and MITF, and consequently, the loss of a key redox effector, apurinic/apyrimidinic endonuclease 1 (APE1)." (PMID 41085102, 2025). "Although genetic alterations, such as MITF mutations and amplifications have been identified in melanoma, MITF activity is more likely influenced by microenvironmental signaling, key epigenetic states, and upstream pathway modifications." (PMID 39976551, 2025). "SOX10 activates the MITF (microphthalmia-associated transcription factor) pathway, which controls genes crucial for melanoma survival and its overexpression is associated with increased tumor aggressiveness and resistance to therapies." (PMID 40647405, 2025). "In melanoma, lineage-specific microphthalmia-associated transcription factor (MITF) is largely involved in the regulation of the differentiated phenotype." (PMID 39970778, 2025). "In melanoma, it has been shown that this gene is regulated transcriptionally by MITF and that its expression is associated with resistance to BRAF inhibition." (PMID 39658088, 2025). "To search for new lncRNA regulators of melanoma biology and vertebrate development we have now identified 506 human candidate melanoma-associated lncRNAs whose loci are bound by MITF and that are transcribed from equivalent regions in the zebrafish genome." (PMID 41336739, 2025). "MITF is a melanocytic lineage-specific transcription factor that has been heavily implicated in malignant melanoma and associated with poor prognosis and metastasis." (PMID 39858514, 2025). "The microphthalmia-associated transcription factor (MITF)-low melanoma, typically characterized by high stemness, produces a CCL2-rich secretome, which promotes the recruitment of TAMs." (PMID 40399946, 2025). "Low MITF expression has been associated with resistance to immune checkpoint inhibitors, particularly in melanoma treated with BRAF/MEK inhibitors." (PMID 39976551, 2025). "Of note, this invasive phenotype of melanoma cells is characterized by microphthalmia-associated transcription factor (MITF) low/AXL high expression." (PMID 41369373, 2025). "In recent years, MITF has been closely linked to the plasticity of melanoma cells, contributing to various melanoma phenotypes characterized by distinct gene expression profiles." (PMID 40872623, 2025).
melanoma (continued). "Three patients had the variant MITF E419K, which has been associated with a 5 times risk of melanoma, and prevents the MITF protein from being SUMOylated, resulting in impaired cellular senescence." (PMID 40766138, 2025). "Surprisingly, melanocytic markers, including MITF, which encodes the master transcriptional factor of melanocytes and melanomas, were also highly upregulated." (PMID 40962798, 2025). "Here, we identified melanoma-associated lncRNAs predicted to be components of the MITF gene regulatory network in human melanoma that have positionally equivalent transcripts in zebrafish." (PMID 41336739, 2025). "MITF is one of the key regulators of melanoma differentiation and has been implicated in playing a role in dedifferentiation, commonly referred to as melanoma phenotype switching." (PMID 40075679, 2025). "The authors analyzed the gene expression levels of ligands and receptors previously associated with the SOX10/MITF axis in melanoma cell lines." (PMID 40872623, 2025). "Loss of DDX3X disrupts MITF regulation, prompting melanoma cells to transition from a proliferative to a more invasive, metastatic phenotype." (PMID 39823244, 2025). "Concurrently, microphthalmia-associated transcription factor (MITF) regulates extracellular ATP release from melanoma cells, providing substrate for CD39 enzymatic activity and fueling adenosine generation." (PMID 41426337, 2025). "The phenomenon of phenotype switching describes this intricate cellular plasticity, in which melanoma cells undergo reversible transcriptional reprogramming that relies on distinct expression levels of microphthalmia-associated transcription factor (MITF)." (PMID 39398277, 2024). "An unbiased translational screening of melanoma phenotypes uncovered the microphthalmia-associated transcription factor (MITF) as a key downstream target of DDX3X in melanomas." (PMID 38539466, 2024). "Tumor heterogeneity associated with microphthalmia-associated transcription factor (MITF) is common, with varied levels conferring different behaviors to melanoma tumors and cells." (PMID 39534873, 2024). "Altogether these results show that miR-579-3p and MITF expression levels are co-regulated in BRAF mutated melanoma and that this co-regulation is linked to activation of BRAF-MAPK signaling." (PMID 38472212, 2024). "Previous studies have demonstrated that TFE3 is a transcription factor expressed in melanoma, which is closely associated with MITF, and plays a crucial role in regulating the sensitivity of cells to iron-induced cell death." (PMID 39440241, 2024). "MITF expression is associated with the cAMP-dependent melanogenic pathway induced by α-MSH in melanoma cells." (PMID 39203053, 2024). "For example, module D upregulates in melanoma cells of pigmentation type 1 and associates with the MITF transcriptional program as well as with oxidative phosphorylation (oxphos)." (PMID 38785552, 2024). "IDO1 inhibitors restore tryptophan and MITF levels, which are reduced in melanoma cells, and lead to the loss of susceptibility of these cells to the antitumor effect of T-cell-derived IFN-γ." (PMID 38351314, 2024). "MITF (microphthalmia-associated transcription factor) controls the growth of melanocytes and acts as an oncogene for melanoma." (PMID 38534309, 2024). "Bulk RNA sequencing from melanoma cohorts has shown that both low and high levels of MITF activity are associated with poor outcomes." (PMID 39092608, 2024). "Such decreases in melanoma cell proliferation have been linked not only to MITF levels but also to regulation by histone demethylase-mediated chromatin remodeling factors." (PMID 38672652, 2024).
melanoma (continued). "Studies have linked MITF function to cellular plasticity in melanoma, and several changes in its expression and activity as a suppressor and mediator of tumour progression have been documented." (PMID 39594467, 2024). "Only one patient (family 6, patient III-1) was found to carry an additional disease-causing variant, c.1273G>A p.Glu425Lys, in the MITF gene (NM_001354604.2), also known to be associated with melanoma." (PMID 38540414, 2024). "The MITF knockdown in melanoma cells results in growth arrest, and the mutation of MITF-M, the main isoform of the MITF in melanocytes, reduces the melanocyte numbers, leading to a white color in mice." (PMID 39000342, 2024). "During metastatic spread, melanoma cells often undergo dedifferentiation toward an invasive phenotype, resulting in reduced expression of microphthalmia-associated transcription factor (MITF)-dependent melanoma antigens and facilitating immune escape." (PMID 39136013, 2024). "This research explores how the low-molecular microphthalmia-associated transcription factor (MITF) specific inhibitor ML329 affects malignant melanoma (MM) cells’ biology." (PMID 38254754, 2024). "Resistance to MEK inhibitors in melanoma cells harboring B-Raf or N-Ras mutations leads to increased expression of transcription factor microphthalmia-associated transcription factor (MITF), which subsequently elevated levels of PGC-1α." (PMID 38921444, 2024). "Early studies indicated that PAX3 was capable of transactivating the promoter of MITF, a transcription factor involved in melanocyte differentiation and an oncogene associated with melanoma cell survival." (PMID 38473380, 2024). "Loss of MIcrophthalmia-associated Transcription Factor (MITF), the master regulator of melanocyte differentiation, induces a reprogramming towards an invasive and stem-like phenotype in melanoma cells." (PMID 38519642, 2024). "We found MITF to be the most enriched upstream regulator, consistent with its well-established role in pigmentation and melanoma risk and progression." (PMID 39802764, 2024). "We here found a mutation in MITF gene, which is recurrent in familial and sporadic melanoma and, more interestingly, has been previously reported in three additional NB patients." (PMID 38351008, 2024). "Another gene associated with AM is MITF, a critical component in the differentiation, survival, and progression of melanocytes, as well as in the pathogenesis of melanoma." (PMID 39519055, 2024). "For example, microphthalmia-associated transcription factor (MITF) plays an important role in skin color and melanoma and the agouti signaling protein (ASIP) is a major regulator of mouse pigmentation." (PMID 37946423, 2024). "GPNMB is a melanocyte-expressed gene with expression dependent on MITF transcription, and the latter was associated with the tricarboxylic acid cycle to regulate the hypoxic response in melanoma." (PMID 38552245, 2024).